MTOR (mechanistic target of rapamycin kinase)
Diseases named in the same sentence as MTOR in open-access papers (continued):
Sharing a sentence is not in itself a finding about the gene and the disease.
epilepsy (continued). "Taken together, our data and previous reports raise the possibility that central glutamine deficiency may upregulate slc1a5 and Slc7a5 gene expression, activate the mTOR pathway, and contribute to astrogliosis and epilepsy, some of the key features of experimental SSADHD." (PMID 33204597, 2020). "However, the role of the mTOR inhibition strategy for the treatment of epilepsy remains viable." (PMID 31611796, 2019). "Because aberrant mTOR signaling is concomitant with an increase in vessel density in epileptic patients, it will be interesting to see if targeting endothelial mTOR might alleviate or lead to a remission of epilepsy symptoms." (PMID 32038280, 2019). "Alternative genetic approaches where Pten is sparsely deleted in a smaller number of neurons, so as not to cause a widespread epilepsy phenotype, may be more advantageous to separate the effects of mTOR dysregulation and seizures." (PMID 29476105, 2018). "However, the molecular changes associated with genetic models of mTOR hyperactivity and epilepsy are not well defined." (PMID 29476105, 2018). "Therefore, mTOR inhibitors, such as rapamycin, may also represent a rational and efficacious strategy for preventing astrocyte injury in epilepsy." (PMID 28588256, 2017). "Participating in mTOR signaling pathway, though the detailed mechanism of the pathology of FYN initiated epilepsy has not been fully revealed, our predicted gene FYN may definitely be an epilepsy associated gene." (PMID 28255556, 2017). "In addition, mTOR inhibitors have shown promise in treating multiple manifestations of TSC, including skin manifestations, cardiac rhabdomyoma, pulmonary lymphangioleiomyomatosis, and epilepsy, which supports the use of mTOR inhibitors as targeted multisystemic therapy for the disease." (PMID 27351628, 2016). "Likewise, inhibition of mTOR with rampamycin blocks excitatory synaptic output of cultured dentate neurons and reactive excitatory synaptogenesis in the brain after epilepsy-induced synaptic reorganization." (PMID 27458339, 2016). "In summary, all these data suggest that there is not a rapamycin dose that can inhibit mTOR for epilepsy without causing any side effects, but 1 mg /kg may be the optimal dose for young rats for suppressing mTOR with relatively few side effects." (PMID 26248290, 2015). "Thus, we investigated the effect of CR on the mTOR pathway and whether CR modified epilepsy generation due to electrical amygdala kindling." (PMID 25814935, 2015). "For example, the components of the mTOR pathway are upregulated after seizures and, most importantly, inhibition of mTOR by rapamycin may ameliorate the development of epilepsy-related pathology and reduce the expression of spontaneous seizures in TLE models." (PMID 24062645, 2013). "Animal models showed that mTOR inhibitors proved to have antiepileptic and even antiepileptogenic effect, decreasing seizures when started after epilepsy onset of seizures, or preventing the development of epilepsy when initiated prior to the onset of seizures." (PMID 24044547, 2013). "Thus, the possibility that VGB could exert at least some of its effects on epilepsy in TSC via interaction with the mTOR pathway is an intriguing, but previously untested, hypothesis." (PMID 23437388, 2013). "Inhibitors of mTOR may improve seizure control in other chronic epilepsy models where the underlying cause of epilepsy is not due to mutations in the TOR pathway." (PMID 22984623, 2012). "mTOR activity is required in dendrites for arbor and spine morphogenesis in some (but not all) studies, raising the possibility that these changes in neuronal morphology may impact seizures and/or epilepsy." (PMID 22984623, 2012). "Furthermore, a ketogenic diet may be an effective treatment for refractory epilepsy because it inhibits the mTOR pathway." (PMID 22761730, 2012). "NEAT1 is differentially expressed in TSC‐related epilepsy and influences neuronal excitability by regulating the PI3K/AKT/mTOR signaling pathway." (PMID 41090516, 2026).
epilepsy (continued). "Targeting NEAT1 with antisense oligonucleotides or siRNAs, in combination with established mTOR inhibitors such as everolimus, represents a promising dual‐approach strategy for the treatment of TSC‐related epilepsy." (PMID 41090516, 2026). "Numerous disorders, including epilepsy, tuberous sclerosis complex (TSC), and cancer, are impacted by mTOR dysregulation." (PMID 39865817, 2025). "Eight individuals with TSC were treated with oral mTOR inhibitors, for seizures or another TSC-related indication, typically after one or more epilepsy surgeries." (PMID 39926610, 2025). "Overstated mTOR activity is related to the progress of TLE, genetic and acquired epilepsy, experimental epilepsy and Lafora disease." (PMID 38006577, 2024). "The significance of various signaling pathways, including the MAPK, mTOR, and WNT/β-catenin pathways, in the modulation of synaptic plasticity and their relevance in both LTP and epilepsy." (PMID 39867454, 2024). "Hyperactive signaling in the mTOR pathway through phosphorylation of S6 and Akt has been observed in FXS individuals post-mortem and in animal models of epilepsy." (PMID 39335388, 2024). "This study included the most common drug-resistant epilepsies (DREs), such as temporal lobe epilepsy with hippocampal sclerosis (TLE-HS), and mTOR pathway-related malformations of cortical development (mTORopathies)." (PMID 38467626, 2024). "Six (32%) participants were on mTOR inhibitors for indications of SEGA (2/6), epilepsy (1/6), renal AMLs (2/6) or lymphangioleiomyomatosis (LAM) (1/6)." (PMID 39352229, 2024). "To date, the literature is sparse in its consolidation of excessive mTOR signaling and ion channel dysfunction in TSC-related epilepsies." (PMID 39253727, 2024). "Everolimus although off label is being prescribed for patients with SEGA, epilepsy, Renal AMLs and Lymphangioleiomyomatosis (LAM), and topical mTOR inhibitor is being used for facial angiofibroma." (PMID 39165678, 2024). "Under normal conditions, mTOR is involved in regulating numerous physiological functions, and dysfunction of these physiological processes may contribute to the pathogenesis of several psychiatric and neurological disorders, including depression, epilepsy, and schizophrenia." (PMID 38365306, 2024). "Accordingly, if the stimulation of synapses is continuous, this leads to further activation of the mTOR/MAPK pathway through RBPs expression and provides a basis for the occurrence of epilepsy." (PMID 38383918, 2024). "A conditional knockout of the downstream repressor of the mTOR pathway specifically within PV+ neurons in mice resulted in an increased sensitivity to kainate- and pentylenetetrazole (PTZ)-induced epilepsy in vivo." (PMID 38563502, 2024). "In an epilepsy mouse model, tau reduction prevented PI3K overactivation and decreased PTEN inhibition, resulting in increased mTOR signaling that increases protein translation." (PMID 38289539, 2024). "Surgery and the use of mTOR inhibitors for SEGA and epilepsy were available for 100% of all patients through referral pathways." (PMID 39165678, 2024). "In 2004, an insightful study revealed overactivation of mammalian target of rapamycin (mTOR) signaling pathway in human specimens of FCD IIb and cortical tubers obtained during epilepsy surgery." (PMID 40217486, 2024). "In sum, these verdicts proposed that metformin attenuates epileptogenesis and epilepsy by indirect mechanisms mainly by modulating inflammatory and oxidative stress disorders, BDNF, α‐synuclein, mTOR pathway and neuroinflammation." (PMID 37737447, 2023). "For example, experimental mTOR inhibitors such as AZD8055 and PF4708671 were shown to be ineffective in mice with epilepsy." (PMID 37737447, 2023). "Given the current evidence, it is necessary to investigate the role of mTOR inhibitors in the treatment of children with drug‐refractory, non‐TSC‐related epilepsy." (PMID 37221133, 2023).
epilepsy (continued). "It has also been demonstrated that the PI3K/Akt/mTOR pathway is overactivated in different ASD and epilepsy mouse models including the Scn1a ± mouse model." (PMID 34980259, 2022). "Research on the use of mTOR inhibitors in the treatment of neurological symptoms of TSC, mainly epilepsy, followed a similar path." (PMID 35572924, 2022). "Treatment with mTOR inhibitors is effective in many manifestations of TSC, such as SEGA tumors, kidney AML, LAM, and epilepsy; however, usually only a partial response is observed." (PMID 35743464, 2022). "On the whole, the effects of mTOR overactivity in TSC patients lead to a multi-system phenotype that includes widespread hamartoma growth, high prevalence of epilepsy and, in up to 50% of the patients, ASD." (PMID 35645731, 2022). "Given the high prevalence of cortical malformations and epilepsy in TSC, a large number of reports has understandably used cortical and hippocampal tissue to study the possible effects of mTOR overactivation on brain morphology and pathology." (PMID 35645731, 2022). "Recently, mTOR-inhibitors, that block mTORC-1 have been approved for the manifestations of TSC, such as renal angiomyolipoma, SEGAs, and epilepsy." (PMID 35359647, 2022). "It is thought that the hyperactivation of mTOR pathway, as seen in other disorders such as sclerosis tuberous, PTEN, and GATOR1 complex deficiency (including DEPDC, NPRL2, and NPRL3 deficiencies), may cause epilepsy through the alteration of normal neural networks." (PMID 36003298, 2022). "Autophagy activity is suppressed in human epilepsy conditions such as tuberous sclerosis complex (TSC), in which mTOR signaling is excessively activated." (PMID 33472865, 2021). "FUS exposure suppresses epileptic activities in acute epilepsy rat models, and this effect seems to be mediated by the PI3K-Akt-mammalian target of rapamycin (mTOR) signaling pathway (Chen S.-G." (PMID 35145384, 2021). "Further examination of mTOR signaling activity and c-fos expression suggested that disruption of the ubtor gene enhances the sensitivity of PTZ-induced epilepsy-like behaviors by up-regulating mTORC1 pathway activity." (PMID 34309811, 2021). "We focused on three genes relevant for seizures and epilepsy: FOS proto-oncogene (c-Fos), inducible cAMP early repressor (Icer) and mammalian target of rapamycin (mTor)." (PMID 33859552, 2021). "Finally, the use of new targeted therapies such as mTOR inhibitors, or cannabidiol, and earlier and better definition of candidates for epilepsy surgery may lead to better outcomes, especially for focal seizures where the seizure control rates have plateaued in the last decade." (PMID 34566842, 2021). "Because mTOR signaling can be inhibited by AMPK activation-mediated phosphorylation of mTOR regulatory proteins, the role of AMPK in the development and intervention of epilepsy has attracted attention." (PMID 34635103, 2021). "Its activation leads to a decrease in the mTOR and TLR4/NF-kB signaling pathways, thus representing a promising therapeutic target for immunoinflammatory disorders like epilepsy." (PMID 34069559, 2021). "Everolimus, an mTOR inhibitor, was effective at reducing focal seizures in TSC, in the first large-scale precision medicine trial in genetically mediated epilepsy." (PMID 34632383, 2021). "In this review, we delineate the spectrum of epilepsies and MCD in the mTORopathies, as well as outlining the influence of mTOR pathway hyperactivation in the pathogenesis of these disorders." (PMID 34632383, 2021). "In cell models of epilepsy and TSC, rapamycin, an mTOR inhibitor, has been shown to decrease seizure frequency and duration, and positively affect cell growth and morphology." (PMID 33643212, 2021). "Subependymal giant cell astrocytomas, renal angiomyolipomas, and epilepsy are the three FDA-approved indications in relation to TSC for the use of everolimus, which is a first generation mTOR inhibitor." (PMID 32222129, 2020).
epilepsy (continued). "Studies have shown that the activity of the mTOR signaling pathway is abnormally increased in epilepsy models, and that GLP-1 analogs can regulate mTOR expression via the AMPK pathway." (PMID 32184723, 2020). "Considering mTOR involvement in cellular functions influencing neuronal excitability, this signaling pathway could participate in the development of epilepsy, as it has been reported in both animal models of epilepsy and in human tissue samples resected from individuals with epilepsy." (PMID 33202963, 2020). "We further aimed at collecting preliminary data on the effects of mTOR inhibitor treatment on TSC-related malformations, epilepsy and neurodevelopment." (PMID 31053163, 2019). "mTOR inhibition is a promising molecular target for the treatment of TSC manifestations, including epilepsy and behavior." (PMID 31053163, 2019). "mTOR inhibitors have also shown improvements in the other manifestations of TSC including renal angiomyolipomas, epilepsy, lymphangioleiomyomatosis, and facial angiofibromas." (PMID 31333563, 2019). "In a mouse model of epilepsy induced by knocking-out the protein phosphatase and tensin homolog (PTEN), mTOR activity increases in neurons." (PMID 31261959, 2019). "mTOR inhibitors are increasingly being used not only for the hamartomatous and oncologic manifestations of TSC, but also as adjunctive therapy for epilepsy and intellectual disability." (PMID 28288694, 2017). "Accordingly, a recent study shows over-activation of pro-inflammatory signaling pathways in astrocytes before epilepsy onset in a mouse model of TSC, pointing to the role of mTOR-mediated inflammatory mechanisms in TSC47." (PMID 28808237, 2017). "Attesting to the role of the mTOR pathway and its inhibition in disorders other than TSC, in a rodent model of temporal lobe epilepsy, rapamycin reduces the sprouting of mossy fiber axons that in part underlies hyperexcitability in the hippocampal dentate gyrus and may underlie epilepsy progression." (PMID 28367137, 2017). "In this review, we will focus on the effect of mTOR and MAPK on RBPs linking local expression control with neuronal hyperexcitability in epilepsy." (PMID 27855659, 2016). "In conclusion, remote expression control that is regulated by mTOR and MAPK provides new approaches to understand epilepsy at a molecular and cellular level." (PMID 27855659, 2016). "Recently, it has been shown that the mechanistic target of rapamycin (mTOR) and mitogen-activated protein kinases (MAPK) are important regulators of synaptic excitability involved in cognitive impairment and epilepsy in animal models as well as human disease." (PMID 27855659, 2016). "In this study, we examined the effect of VGB on epilepsy in a mouse model of TSC, including possible interactions with the mTOR pathway." (PMID 23437388, 2013). "It has thus been hypothesized, that the critical time window for mTOR inhibitors may lie in early infancy, before TSC-related symptoms such as early-onset epilepsy and infantile spasms as sign of disruptive brain maturation occur." (PMID 39762914, 2025). "These epilepsies are not specifically related to enhanced mTOR signaling but instead, encompass a wide range of idiopathic epilepsies with most having unclear origins." (PMID 40246555, 2025). "Recently, a preclinical study has shown that targeting different upstream components of the PI3K-AKT–MTOR pathway but not MTOR can acutely treat epilepsy, suggesting that epilepsy is more than channelopathies and TORopathies." (PMID 40529445, 2025). "The histopathological dysmorphic neurons in patients with drug-resistant epilepsy with FCD exhibited enlarged cell soma size, increased expression of the nonphosphorylated neurofilament protein (SMI) and upregulation of the mTOR pathway, reminiscent of morphological features of senescent cells." (PMID 40026248, 2025).
epilepsy (continued). "The use of mTOR inhibitors as a therapeutic option in TSC is well-established in postnatal settings, with proven efficacy in reducing tumour size and controlling refractory epilepsy in some cases." (PMID 39518472, 2024). "mTOR.13.o showed conservation in control and all epilepsy cohorts but, similarly, no change in coexpression comparing disease and control cohorts." (PMID 38467626, 2024). "We hypothesize that mTOR inhibitors could help manage or prevent other TSC-related conditions, particularly neurological issues like epilepsy and CNS lesions, potentially improving neurodevelopmental outcomes." (PMID 39518472, 2024). "Finally, the mTOR pathway represents a shared mechanism between LTP and epilepsy, primarily through its regulation of neuronal excitability and synaptic plasticity." (PMID 39867454, 2024). "The interplay between the mTOR pathway in LTP and epilepsy presents several intriguing questions." (PMID 39867454, 2024). "The availability of mTOR inhibitors for clinical treatment of TSC patients with growing angiomyolipoma, SEGA, LAM, and as adjuvant therapy for refractory epilepsy positively impacts the clinical outcome and highlights the need for early diagnosis of the disease." (PMID 39596632, 2024). "Patients with TSC2 variations may benefit from mTOR inhibitors like everolimus, which have demonstrated a >50% reduction in seizure frequency in TSC-related epilepsy patients." (PMID 39906551, 2024). "Furthermore, mTOR, the most intrinsic properties of GBM, depicting its specific molecular profile, directly influences the development of epilepsy." (PMID 36831117, 2023). "Therefore, rapamycin and everolimus by inhibiting the mTOR pathway, activating the expression of FK506-binding protein and induction of autophagy can attenuate seizure activity and the development of epilepsy." (PMID 37880579, 2023). "By analyzing the differentially expressed genes (DEGs) in epilepsy rat models with or without electroacupuncture treatment, the functional enrichment of DEGs was found mainly in the mTOR signaling pathway and autophagy." (PMID 37221133, 2023). "Amongst the most well-known examples of non-ion channel-associated epilepsy genes are TSC1 and TSC2, components of the mammalian target of rapamycin (mTOR) pathway." (PMID 37834053, 2023). "However, both mTOR and GSK3 upstream are the negative regulators of autophagy leading to failure of autophagy as in Lafora disease which is an autosomal recessive epilepsy characterized by resistance epilepsy and dementia." (PMID 37880579, 2023). "Finally, components along the mTOR pathway, including PTEN, PI3K, AKT that are all reported in epilepsy patients remain underexplored in the context of epilepsy with PSC-derived systems." (PMID 35359577, 2022). "Some evidence also exhibits that the mTOR signal participates in temporal lobe epilepsy (TLE), chemoconvulsive compounds-mediated experimental epilepsy, and other epileptogenesis forms of genetic or acquired epilepsy, such as traumatic brain injury and Lafora disease (LD)." (PMID 36078029, 2022). "The link between UBE3A and epilepsy or alteration in the mTOR pathway has not been extensively studied in human in vitro models until recently." (PMID 35359577, 2022). "Recent evidence suggests that the signaling pathways involving mTOR and MAPK activation are important regulators of synaptic excitability and might be responsible for epilepsy and the concomitant cognitive impairment." (PMID 34122302, 2021). "Given the evidence to date, a logical next step is to investigate the role of mTOR inhibitors in the treatment of children with medically refractory non-TSC epilepsy, particularly those children who have also failed resective surgery." (PMID 33643212, 2021). "The role of microglia and the microglial mTOR signaling network in epilepsy has recently garnered significant attention." (PMID 33472865, 2021).